Y_RNA (Y RNA )
Gene: Miscellaneous RNA gene on chromosome 14 (93,397,139 to 93,397,234, reverse strand). Ensembl gene ENSG00000202306.
Homologues: Orthologues: chimpanzee Y_RNA (97% identical), guinea pig Y_RNA (84% identical). Paralogues in human: RNY4 (92% identical), RNY4P6 (90% identical), Y_RNA (90% identical), RNY4P14 (89% identical), RNY4P7 (89% identical), RNY4P10 (88% identical), RNY4P24 (88% identical), Y_RNA (88% identical), RNY4P13 (86% identical), RNY4P17 (86% identical), RNY4P3 (86% identical), RNY4P19 (85% identical), and 91 more.